GBA1 (glucosylceramidase beta 1)
Diseases named in the same sentence as GBA1 in open-access papers (continued):
Sharing a sentence is not in itself a finding about the gene and the disease.
cognitive decline (77 papers, 2013 to 2026). "In case of idiopathic PD, patients with GBA1 mutations are characterized by an earlier age at onset, greater cognitive decline, and a greater likelihood of atypical clinical manifestations." (PMID 39906200, 2025). "These GBA1-associated PD (GBA1-PD) cases account for ~10% of all PD and are characterized by earlier onset, faster progression, and more severe cognitive decline." (PMID 41009720, 2025). "We also found an association between constipation and GBA1 status (OR = 2.05, 95% CI = 1.18–3.64, P = 0.012), which is interesting as constipation has also been found to be predictive of cognitive decline in PD28,29." (PMID 39420034, 2024). "GBA1-associated PD phenotypically can be characterized mostly as sporadic PD but is usually associated with an earlier age of onset, while cognitive decline and psychiatric symptoms can be dominating signs as well." (PMID 38153678, 2024). "FOG is a relatively common disabling symptom in PD patients with GBA1 mutations, which is affected by motor disability and cognitive decline." (PMID 38089969, 2023). "PD patients with GBA1 mutations exhibit up to three times higher risk of developing cognitive decline compared to iPD." (PMID 36768367, 2023). "We found that FOG in individuals carrying GBA1 mutation was influenced by motor severity and cognitive decline." (PMID 38089969, 2023). "Motor disability and cognitive decline are likely contributors to the occurrence of FOG among carriers of GBA1 mutations." (PMID 38089969, 2023). "PD patients with GBA1 mutations exhibit a threefold increased risk of cognitive decline, affecting working memory, executive and visuospatial functions." (PMID 35932311, 2022). "As pathogenic GBA1 mutations are associated with early and more advanced cognitive decline in PD patients, the demonstration of this phenotype in this and other GBA1 D409V KI mouse models is of interest." (PMID 34106956, 2021). "Our findings should be considered in the context of several large-scale studies that describe more rapid cognitive decline in patients with PD who are heterozygotes for mutations in GBA1." (PMID 29845374, 2018). "Patients who harbor GBA1 mutations present a higher prevalence and severity of bradykinesia, motor complications, cognitive decline and anxiety." (PMID 27126635, 2016). "Notably, some phenotypes, such as cognitive decline, can emerge with the GBA1 mutation alone, echoing the early cognitive symptoms observed in GBA1-PD patients." (PMID 41465340, 2025). "Mutations in the GBA1 gene are among the most prevalent genetic risk factors for PD, with severe variants associated with earlier symptom onset, faster disease progression, and greater cognitive decline." (PMID 40687116, 2025). "Importantly, this clinical phenotype is dependent on the GBA1 genotype with severe mutations predisposing to more prominent motor impairment and cognitive decline as compared to GBA1 risk variants and mild mutations." (PMID 38649346, 2024). "Furthermore, GBA1 mutation carriers with PD are on a trajectory to cognitive decline, and they are more prone to present with the postural instability gait difficulty phenotype compared with non-carriers." (PMID 38089969, 2023). "The study of genetic subtypes of PD (e.g., LRRK2-PD and GBA1-PD) has made it very clear that PD subtypes exist; in the case of the subtype of PD linked to GBA1 mutations, patients rarely develop a tremor, but and often suffer from early cognitive decline." (PMID 34312398, 2021). "Early identification of GBA1 mutation carriers who are at increased risk of cholinergic decline might therefore offer a window for intervention to ameliorate or prevent cholinergic degeneration and ultimately cognitive decline." (PMID 38951174, 2024). "Neuropathologically, GBA1-linked DLB shows greater cortical Lewy body accumulation and more rapid cognitive decline compared to sporadic DLB and short survival." (PMID 41465169, 2025).
cognitive decline (continued). "Results on cognitive outcomes showed even more significant differences between iPD and severe GBA1-PD when analyses were repeated excluding patients with DBS (N = 36), suggesting that genetic GBA1 status itself plays an independent role in cognitive decline." (PMID 41034226, 2025). "An earlier onset by ~2 to 10 years accelerated progression of motor and cognitive decline, and poorer survival rates occur in GBA1‐PD cohorts compared with their sporadic counterparts." (PMID 39258449, 2024). "Risk/benefit analyses have been discussed on the clinical utility of subthalamic nucleus deep brain stimulation in GBA1‐PD cohorts given mixed reports suggesting a potential worsening in cognitive decline." (PMID 39258449, 2024). "Ongoing longitudinal studies aim to identify cognitive decline, other NMS and motor abnormalities in individuals harbouring GBA1 mutations prior to the onset of PD symptoms." (PMID 35932311, 2022). "Importantly, our findings reveal that the observed rates of cognitive decline remained unaffected by the presence of GBA1 and APOEε4 carrier status." (PMID 40051075, 2025). "Furthermore, cognitive decline is accelerated in PD patients who carry both APOE4 and GBA1 variants compared to single variant carriers." (PMID 37947642, 2023). "Specifically, some studies have raised attention to the fact that PD carriers of GBA1 variants (PD-GBA1) may have a worse DBS outcome, possibly due to an accelerated progression of cognitive decline." (PMID 37122287, 2023). "Furthermore, local brain atrophy was reported in GBA1-PD patients resulting directly in varying intensity of cognitive decline." (PMID 36768367, 2023). "Compared to non-GBA1-associated PD, GBA1-associated PD shows an earlier onset of the disease and a higher prevalence of non-motor symptoms, such as cognitive decline." (PMID 34194386, 2021). "While LRRK2 and GBA1 mutations are both associated with increased basal forebrain volume at asymptomatic stages, this increase persists at the symptomatic PD stage only in LRRK2 and might be related to slower cognitive decline in these patients." (PMID 38951174, 2024). "To date, no study has yet investigated the potential effects of GBA1 mutations on cholinergic function and whether the biochemical consequences of these might accelerate proteinopathy related to cognitive decline." (PMID 35179198, 2022). "In conclusion, while LRRK2 and GBA1 mutations are both associated with a specific increase in basal forebrain volume at the asymptomatic stage, this increase persists at the symptomatic PD stage only in LRRK2 carriers and might be related to the slower rate of cognitive decline in these patients." (PMID 38951174, 2024). "Whereas in sporadic PD the APOE ε4 allele was associated with faster cognitive decline than APOE ε3 or ε2 alleles, no APOE effect was observed in GBA1-PD or LRRK2-PD." (PMID 41730900, 2026). "Interestingly, human subjects that carry both the LRRK2 G2019S variant and an additional variant in GBA1 do not have a worse clinical course of PD than those that carry a variant in either gene and, in fact, may have a beneficial effect with respect to cognitive decline." (PMID 40770658, 2025). "For example, common genetic variation at GBA1 and APOE affects the rate of cognitive decline." (PMID 37842125, 2023). "Interestingly, this retrospective study reported a more rapid cognitive decline in the group of PD-GBA1 treated with STN-DBS compared to non-GBA1 carriers treated with DBS, non-GBA1 carriers not treated with DBS and PD-GBA1 not treated with DBS." (PMID 39199492, 2024).
dementia with Lewy bodies (75 papers, 2014 to 2026). "A recent study using 943 autopsy-confirmed Lewy body disease found that those with GBA1 mutations exhibited lower Braak neurofibrillary tangle stage and Thal amyloid phase and more severe Lewy-related pathology." (PMID 41185066, 2025). "In total, four GBA1 variants were found: three have been already associated with PD (p.N409S, p.L483P, and p.T408M) and one with Lewy-body dementia (p.H294Q)." (PMID 39766872, 2024). "A study by Shiner and colleagues evaluated the effect of GBA1 variants on the clinical characteristics and progression of Dementia with Lewy Bodies (DLB) patients in a 35-patient Ashkenazi Jewish cohort." (PMID 39766872, 2024). "Both homozygous and heterozygous carriers of mutant GBA1 alleles are at increased risk for sporadic and complex neurodegenerative diseases including Parkinson’s disease (PD) and dementia with Lewy Bodies (DLB)." (PMID 37045813, 2023). "Post-mortem analysis of brains of Lewy bodies dementia (LDB) patients carrying GBA1 mutations showed an abnormal UPR response that was associated with ER stress." (PMID 37569538, 2023). "Deficits in the lipid handling genes APOE and GBA1 are the most significant genetic risk factors for Lewy body dementia and related dementia syndromes." (PMID 37947642, 2023). "Several heterozygous variants of the glucocerebrosidase gene (GBA1) have been reported to increase the risk of Parkinson’s disease (PD) and dementia with Lewy bodies (DLB)." (PMID 37019925, 2023). "GBA1 mutations also elevate the risk for dementia with Lewy bodies (DLB), providing further insight into the role of GCase in PD-related synucleinopathies." (PMID 37886493, 2023). "GBA1 mutation-positive individuals exhibit an increased risk of developing Dementia with Lewy Bodies (DLB; odds ratio, OR ~ 8), notably higher than that for PD (OR 3.5–6)." (PMID 35932311, 2022). "Glucocerebrosidase gene (GBA1) variants are found in 10–15% of PD cases and are numerically the most important risk factor for PD and dementia with Lewy bodies." (PMID 35179198, 2022). "In the past few years, accumulating evidence was provided sustaining a direct genetic link between GBA1 homo- and heterozygous mutations and increased incidence of synucleinopathies, including Parkinson’s disease (PD) and dementia with Lewy bodies (DLB)." (PMID 34062940, 2021). "CTSD protein and activity are reduced in the frontal cortex of PD and Lewy body dementia brains with GBA1 mutation." (PMID 31634558, 2020). "Currently, mutations in GBA1 are one of the most common genetic risk factors for PD, as well as dementia with Lewy bodies (DLB)." (PMID 32509770, 2020). "The presence of a direct link between GBA1 mutations and synucleinopathies such as PD and dementia with Lewy bodies (LBD) has been uncovered by multicenter genetic studies." (PMID 28835999, 2018). "More recently, heterozygous mutations in the GBA1 gene were found to be among the most common genetic associations with sporadic PD and dementia with Lewy bodies (DLB)." (PMID 27019408, 2016). "GBA1 dysfunction has also been recently linked to Parkinson’s disease (PD) and Dementia with Lewy bodies (DLB)." (PMID 25763858, 2015). "Many studies have demonstrated the association between GBA1 gene variants and Lewy body dementia." (PMID 41185066, 2025). "In addition, GBA1 mutations are also the most important hereditary risk factor linked to Dementia with Lewy Bodies (DLB)." (PMID 39766872, 2024). "Pathologically, one study revealed an inverse relationship between the frequency of GBA1 mutations/polymorphisms and the severity of comorbid AD in Lewy body dementia, suggesting that GBA1 genetic variants may influence the development of Lewy body dementia independent of comorbid AD." (PMID 41185066, 2025). "GBA1 mutations (heterozygote and homozygote) are numerically the most important risk factor for the development of PD and for Dementia with Lewy bodies (DLB)." (PMID 35179198, 2022).
dementia with Lewy bodies (continued). "Indeed, GBA1 GD-causative mutations are broadly recognized as the most common genetic risk factor for the development of Parkinsonism and Lewy Body disease that not only increases susceptibility to PD, but also drives the disease progression with an earlier onset or increased severity." (PMID 27598339, 2016). "In PD and Lewy body dementia (LBD), GBA1 mutations and age-associated loss of GBA1 function alter lysosomal glycosphingolipid metabolism and contribute to α-synuclein pathology." (PMID 41278977, 2025). "There is overlap between the splicing event changes detected in the GBA1 mutant cell line and the altered transcript isoforms from Lewy body disease brain biopsy RNA-seq data." (PMID 40950074, 2025). "Subsequent multisite studies demonstrated GBA1 mutations in approximately 7.6% of DLB patients and 3.6% of individuals with both Lewy body disease and Alzheimer’s neuropathology." (PMID 37629187, 2023). "Notably, these variants also significantly increase the risk of developing Parkinson’s disease (PD) and Dementia with Lewy Bodies (DLB), making GBA1 the most common genetic risk factor for PD." (PMID 40362629, 2025). "Moreover, variants of GBA1 are also known to increase the risk of dementia with Lewy bodies (DLB)." (PMID 38329128, 2024). "Nevertheless, the GCase protein was identified in 32–90% of Lewy bodies in patients with GBA1-related PD or Dementia with Lewy bodies (DLB) and less than 10% of Lewy bodies in patients with idiopathic PD, suggesting a possible interaction between GCase and α-synuclein." (PMID 37047309, 2023). "Decreased CTSD activity has been found in brains of PD and dementia with Lewy body patients with and without GBA1 variants and correlated with both reduced GCase activity and GBA1 gene expression." (PMID 35179198, 2022). "Decreased CTSD activity has been reported in brains of PD and dementia with Lewy body patients with and without GBA1 mutation, and correlated with both reduced GCase activity and GBA1 gene expression." (PMID 31634558, 2020). "Given the similarities to the GBA1 studies, our current results suggest that the reduced expression of CTSD leads to accelerated disease progression in Lewy body diseases." (PMID 26448324, 2015). "Interestingly, GBA1, BIN1 and TMEM175, which are associated with case–control Lewy body disease GWAS11, did not appear significant when comparing LBD-D with LBD-ND." (PMID 38978726, 2024). "Heterozygous GBA1 variants associated with reduced GCase activity are important risk factors for both PD and dementia with Lewy bodies (DLB), and a substantial portion of patients with these disorders have reduced GCase activity albeit not carrying GBA1 variants." (PMID 38883744, 2024).
synucleinopathies (71 papers, 2012 to 2025). "While considerable progress has been made in delineating GBA1-linked mechanisms in synucleinopathy, many gaps remain." (PMID 41465169, 2025). "Recent evidence questions the assumption that GBA1-related lysosomal dysfunction causes a uniform synucleinopathy, revealing distinct regional effects and disease paths." (PMID 41465169, 2025). "In these GBA-associated PD patients the α-synuclein pathology is more prominent, and recent data suggest a link between α-synucleinopathies and GBA1 mutations." (PMID 40333681, 2025). "Cell-type vulnerability in GBA1-associated synucleinopathies is attributed to intrinsic metabolic stress and network dysfunction, not just GCase deficiency." (PMID 41465169, 2025). "GBA1 mutations are well established as the most common genetic risk factor for PD and other synucleinopathies." (PMID 38641924, 2024). "Our results implicate acid ceramidase in the pathogenesis of GBA1-associated PD, suggesting that this enzyme is a potential therapeutic target for treating synucleinopathies caused by GCase deficiency." (PMID 36752535, 2023). "It has been observed that GBA1 mutations are one of the most impactful risk factors for developing α-synucleinopathies such as PD and DLB." (PMID 36768367, 2023). "Especially, personalized targeted therapies are of utmost interest in the case of various genetic variants of GBA1, either in the potential treatment of GD or in α-synucleinopathies." (PMID 36768367, 2023). "One of the studies demonstrated a significant association between GBA1 mutation carrier status and other synucleinopathies such as DLB." (PMID 37304077, 2023). "This strong association spurred an upsurge in research on the cellular mechanism underlying the GBA1-PD link, as well as the potential of GCase as a therapeutic target for the synucleinopathies." (PMID 37886493, 2023). "Loss of function mutations in the GBA1 gene that encodes GCase are one of the leading genetic risk factors for the synucleinopathies of PD and DLB." (PMID 36369100, 2022). "Preclinical evaluation of venglustat, a brain-penetrant inhibitor of glucosylceramide synthase, reduced asyn pathology and the associated cognitive decline in mouse models of GBA1-related synucleinopathy." (PMID 35614915, 2022). "Rare variants in the beta-glucocerebrosidase gene (GBA1) are common genetic risk factors for alpha synucleinopathy, which often manifests clinically as GBA-associated Parkinson’s disease (GBA-PD)." (PMID 33402667, 2021). "Overall, there is strong support for the notion that GBA1 mutations exert a large effect on susceptibility for a spectrum of synucleinopathies." (PMID 34149605, 2021). "Although GD primarily affects peripheral tissues, recent observations have shown that heterozygous mutations in the GBA1 gene represent the most important genetic risks, not only in PD but also in other synucleinopathies (LBD included)." (PMID 31277513, 2019). "Although mutations in genes such as LRRK2, PINK1 and DJ-1 have often been implicated in the pathophysiology of synucleinopathies, GBA1 mutations are the ones showing the highest prevalence." (PMID 28835999, 2018). "Polymorphisms in genes encoding lysosomal enzymes, acid sphingomyelinase (SMPD1 gene), and β-glucocerebrosidase (GBA, GBA1 gene), are also risk factors for synucleinopathies." (PMID 29021741, 2017). "Mutations in GBA1 are an important risk factor for the development of several synucleinopathies including PD, DLB and MSA." (PMID 27482815, 2016). "The present report extends this observation to include murine models of synucleinopathies that harbor WT alleles of Gba1 (e.g. Thy1-SNCA transgenic mice)." (PMID 27126635, 2016). "In recent years, intense research on the link between GBA1 mutations and synucleinopathies, as well as the development of novel therapeutics, has prompted the development of novel cell models." (PMID 27482815, 2016).